TNFSF4 (TNF superfamily member 4)
Diseases named in the same sentence as TNFSF4 in open-access papers (continued):
Sharing a sentence is not in itself a finding about the gene and the disease.
breast carcinoma (25 papers, 2012 to 2025). "We found that TNFSF4 was highly expressed in all kinds of breast carcinomas, and its aberrant overexpression was associated with shorter overall survival and disease-free survival." (PMID 34545132, 2021). "Correlation heatmap analysis and protein-protein interaction (PPI) network demonstrated strong associations among TNFSF4, TP63, CD24, ESR1, and PRLR, suggesting their potential roles in HR+ breast cancer progression." (PMID 40612672, 2025). "High expression of TNFSF4 was universally identified in breast carcinoma and pointed to poorer survival outcomes." (PMID 34545132, 2021). "The AA haplotype of TNFSF4 (order of SNPs: rs844648, rs10912580) has been shown to be correlated with the occurrence of breast cancer." (PMID 33287909, 2020). "TNFSF4 was explored to be closely related to breast carcinoma." (PMID 40447854, 2025). "Elevated levels of TNFSF4 have been found in patients with gastric cancer, esophageal cancer, liver cancer, and breast cancer, which suggests that TNFSF4 may be an effective candidate for cancer treatment." (PMID 37511932, 2023). "For the first time, we identified the oncogenic features of TNFSF4 in breast carcinoma." (PMID 34545132, 2021). "There are only limited studies exploring the possible functions of TNFSF419,20, and the roles of TNFSF4 in breast carcinoma are unknown." (PMID 34545132, 2021). "Moreover, the potential immunotherapeutic approach of TNFSF4 blockade showed underlying effects on stem cell expansion, which more strongly and specifically demonstrated the potential effects of applying TNFSF4 blockade-based immunotherapies in breast carcinomas." (PMID 34545132, 2021). "Specifically, CD112, TNFSF4, TNFSF18, and LGALS9 were significantly overexpressed in breast carcinomas, strongly suggesting potent and valuable effects." (PMID 34545132, 2021). "Furthermore, PD-L1, CD112, TNFRSF14, TNFSF4, TNFSF18, CD48, and LGALS9 were analyzed for abnormal expression patterns in breast carcinomas." (PMID 34545132, 2021). "Similarly, the combination of TNFSF4 (OX40L) fusion protein and poxvirus-based cancer vaccine (MVA-Twist-TRICOM) can also be used effectively to inhibit lung metastasis of breast cancer by increasing the infiltration of CD4+CD8+ T cells and the production of IFN-γ and TNF-α." (PMID 34367975, 2021).
allergic disease (20 papers, 2017 to 2024). An immune response that occurs following re-exposure to an innocuous antigen, and that requires the presence of existing antibodies against that antigen. "Indeed, the adjuvant CT, orally fed to mice, generates allergy in vivo by inducing upregulation of DC genes that prime for Th2 responses, such as Irf4, Tnfsf4, and Jagged2, in the PPs and MLNs." (PMID 34684302, 2021). "Accumulating data suggest that the interaction between TNFSF4 and its receptor, TNFRSF4, not only plays crucial roles in the induction of anti-tumor immunity, allergies and autoimmunity, but also suppresses the development of adaptive T regulatory (TR1) cells." (PMID 29285231, 2017).
Autoimmunity (19 papers, 2008 to 2025). The occurrence of an immune reaction against the organism's own cells or tissues. "PGx predictors of capecitabine ADRs are SNPs in DPYD*5, MTHFR and near TNFSF4 (OX40L), a gene implicated in autoimmunity." (PMID 34948113, 2021). "Tnfsf4-expression, encoding OX40L, has been associated with autoimmunity and Th17 cell differentiation, but reported to be expressed only in cDC2 cells and not in cDC1 cells 71,72." (PMID 35418673, 2022). "There are some gene variants evaluated to be involved and are common in the pathogenesis of the four diseases of cytokine pathways (e.g., IRF5, STAT4, and TNFSF4) leading to the development of autoimmunity." (PMID 26339139, 2015). "Moreover, TNFSF4 stimulates B-cell proliferation that results in cell hyperactivity in autoimmune disorders." (PMID 33516274, 2021). "There is an interaction between TNFSF4 and TRAF2 to modulate apoptosis through NF-KB pathway which is involved in T-cell-mediated autoimmunity." (PMID 33516274, 2021). "Lentiviral transduced MSCs with T/natural killer (NK) cell-targeting chemokine CXCL9 and immunostimulatory factor OX40 ligand (OX40)/tumor necrosis factor superfamily member 4 (TNFSF4) to tumor sites improve the recruitment of CD8+ T and NK cells and reduce the autoimmunity PD-1 and MHC-1 response." (PMID 39063032, 2024).
glioblastoma (13 papers, 2015 to 2025). The most malignant astrocytic tumor (WHO grade IV). "Our model genes are also associated with immune therapy response in glioblastoma, including T cell co-stimulatory molecules like TNFRSF18 and TNFSF4." (PMID 38365809, 2024). "Similar associations were observed in the CGGA-glioblastoma cohort for CD40, CD276, TNFRSF14, and TNFSF14, except for TNFSF4 and TNFRSF18." (PMID 38365809, 2024). "The expression of the TNFSF4 gene also correlated with the response of recurrent glioblastoma patients to autologous NK cell therapeutics, serving as a potential biomarker of responsiveness." (PMID 39201666, 2024). "Based on these findings, we established a risk signature comprised of CD276, TNFRSF14, TNFSF14, TNFSF4, CD40, and TNFRSF18 to predict OS and response to immune checkpoint blockade in glioblastoma patients." (PMID 38365809, 2024). "In addition, we obtained representative IHC staining images of CD276, TNFSF4, TNFRSF14, CD40, TNFSF14, and TNFRSF18 in both normal tissues and glioblastoma samples from the Human Proteome Atlas." (PMID 38365809, 2024).
glioma (13 papers, 2015 to 2026). A benign or malignant brain and spinal cord tumor that arises from glial cells (astrocytes, oligodendrocytes, ependymal cells). "Additionally, our results identified specific immune-related molecules—TNFSF4, HLA-DRA, and ENTPD1—that were significantly correlated with the crotonylation-associated risk score, further linking crotonylation pathways to the regulation of the immune microenvironment in gliomas." (PMID 40636690, 2025). "The results of our investigation showed a strong relationship between the expression of SMARCAL1 and several immune checkpoint genes, including CD276, NRP1, TNFSF4, CD40, CD200, and CD80 in Glioma, LUAD, LIHC, KIRC, and UCEC." (PMID 39994264, 2025). "Through analysis of glioma samples in the CGGA and TCGA databases, we found that CDCA7 expression level was significantly correlated with tumor-related immunosuppressive molecules, including CD80, CD276, CD28, PDCD1LG2, and TNFSF4." (PMID 37510310, 2023).
bladder cancer (8 papers, 2019 to 2023). "In this study, the researchers found that the mRNA, as well as protein expression of TNFSF4 in normal bladder tissues adjacent to cancer, was higher in comparison to that among bladder cancer tissues." (PMID 36733811, 2022). "Subsequent in vitro experiments on human bladder cancer cell lines indicated that overexpression of this piRNA led to inhibition of apoptosis and colony formation, possibly through regulation of Tumor Necrosis Factor Superfamily Member 4 (TNFSF4)." (PMID 33673453, 2021). "Moreover, the TNFSF4 expression in cancer-free serum was found higher than that in bladder cancer serum." (PMID 36733811, 2022). "Researchers showed a possible interaction with Tumor Necrosis Factor Superfamily Member 4 (TNFSF4) hypothesizing that piRABC may promote Bladder Cancer cell apoptosis by up regulation of TNFSF4." (PMID 30705933, 2019). "Thus, it can be seen that the TNFSF4 gene is a potential target gene of piRABC, and piRABC may also be a potential therapeutic target for bladder cancer." (PMID 36733811, 2022). "Therefore, the down-regulation of piRABC expression may promote cell proliferation, and colony formation and inhibit apoptosis of bladder cancer by affecting the TNFSF4 gene and thus down-regulating TNFSF4 protein." (PMID 36733811, 2022).
lupus nephritis (8 papers, 2011 to 2026). Glomerulonephritis in the context of systemic lupus erythematosus. "As it was the first time to link TNFSF4 risk allele and lupus nephritis (LN), a further independent replication was needed, especially from the Asian populations due to their higher prevalence of LN than that in the Caucasians." (PMID 23936824, 2013). "The clearest examples are the associations of a TNFSF4 SNP with lupus nephritis, and the protection conferred by STAT4 for oral ulcers." (PMID 23049788, 2012). "However, some of our results were concordant in direction and magnitude as between the TNFSF4 SNP and lupus nephritis, and STAT4 SNP and protection from oral ulcers or risk to immunologic disorder." (PMID 23049788, 2012). "Although renal damage was infrequent, it was significantly associated with rs2205960 of TNFSF4 gene, which was previously associated with SLE susceptibility and lupus nephritis (LN)." (PMID 35743441, 2022). "Our data firstly replicated the association of TNFSF4 with renal disorder in SLE patients in the Chinese population, which supported that TNFSF4 may act as a marker of lupus nephritis." (PMID 23936824, 2013). "Our data nevertheless supported that TNFSF4 may act as marker of lupus nephritis." (PMID 23936824, 2013). "Strong TNFSF4 expression was detected in lymph nodes and “apparently normal” paratumor renal biopsy but not in renal biopsies from lupus nephritis." (PMID 23936824, 2013). "In all of the renal tissues including type I, II, III, IV, and V lupus nephritis, no obvious expression of TNFSF4 was detected in glomeruli, tubules, and vasculature." (PMID 23936824, 2013). "Less TNFSF4 may lead to induction of IL-10-producing CD4(+) type 1 regulatory T (Tr1) cells, while higher IL-10 was an intrarenal biomarker of disease activity in lupus nephritis." (PMID 23936824, 2013). "But it observed TNFSF4 rather than TNFRSF4 expressed in a granular distribution predominantly along the epithelial side of the glomerular capillary wall, only in type IV lupus nephritis." (PMID 23936824, 2013).
rheumatoid arthritis (8 papers, 2014 to 2023). A chronic, systemic autoimmune disorder characterized by inflammation in the synovial membranes and articular surfaces. "TNFSF4, the gene encoding OX40L, has been determined by GWAS to have risk alleles in SLE, rheumatoid arthritis (RA), and multiple sclerosis, further suggesting an involvement of OX40 and OX40L interaction mediated Tfh pathway in disease conditions." (PMID 30123218, 2018).
lung carcinoma (7 papers, 2021 to 2025). "Our findings indicate that the combination of CEACAM1, TNFSF4, GEM, CD47, VTCN1, and TANlncSig in squamous cell carcinoma can effectively stratify patients by prognosis, highlighting these immune checkpoint receptors as potential therapeutic targets against advanced lung cancer." (PMID 36386809, 2022).
hepatocellular carcinoma (6 papers, 2019 to 2023). A malignant tumor that arises from hepatocytes. "Due to the importance of ICI in the immunotherapy of hepatocellular carcinoma, we further analyzed the differential expression of immune checkpoint genes between the two groups, and found that the expression in the low-risk group is higher, while the results for TNFSF4 and CD276 are the opposite." (PMID 36672493, 2023).
lung adenocarcinoma (6 papers, 2022 to 2024). A carcinoma that arises from the lung and is characterized by the presence of malignant glandular epithelial cells. "A previous study demonstrated that TNFSF4 could facilitate chemoresistance in lung adenocarcinoma by inhibiting the apoptosis of tumor cells." (PMID 38937712, 2024).
myocardial infarction (6 papers, 2011 to 2025). Gross necrosis of the myocardium, as a result of interruption of the blood supply to the area, as in coronary thrombosis. "A polymorphism in the promoter region of the TNFSF4 gene has been demonstrated to be associated with the risk of myocardial infarction." (PMID 39943110, 2025). "We have previously shown that genetic variants in TNFSF4 are associated with myocardial infarction (MI) in women." (PMID 21445270, 2011). "Several studies reported the association between the rs3850641 polymorphism of the TNFSF4 gene and the risk of myocardial infarction (MI)." (PMID 29921578, 2018).
narcolepsy (6 papers, 2013 to 2024). A sleep disorder characterized by a tendency for excessive sleepiness during the day which occurs even after adequate sleep in the nighttime. "In addition to a strong signal in the T cell receptor alpha (TRA@), variants in two additional narcolepsy loci, Cathepsin H (CTSH) and Tumor necrosis factor (ligand) superfamily member 4 (TNFSF4, also called OX40L), attained genome-wide significance." (PMID 23459209, 2013). "Our study of nearly 2000 narcolepsy cases compared to 10,000 controls underscored important roles for HLA DQB1*06:02 and the T cell receptor alpha genes and implicated two additional genes, Cathepsin H and TNFSF4/OX40L, in disease pathogenesis." (PMID 23459209, 2013).
colon carcinoma (5 papers, 2018 to 2025). "For example, the TNFSF4 gene is associated with epigenetic regulation in colon cancer." (PMID 35991839, 2022). "Hence, using MSC engineering to deliver CXCL9 (and also immunostimulatory factors OX40L and TNFSF4) triggers an increase in the CD8 and NK cells expressing granzyme B in colon tumor models." (PMID 36429101, 2022).
pancreatic cancer (5 papers, 2018 to 2023). "Several immune checkpoints, including TNFSF4, ICOS, CTLA4, and PDCD1, have been identified as playing crucial roles in the progression of pancreatic cancer." (PMID 37753069, 2023).
psoriasis (5 papers, 2021 to 2025). An autoimmune condition characterized by red, well-delineated plaques with silvery scales that are usually on the extensor surfaces and scalp. "Another study, examining whole blood methylation differences in psoriasis, identified three regions on chromosome-8, and chromosome-6 loci MICA, IRIF1, PSORS1C3, and TNFSF4 as hypermethylated in paternally transmitted disease, while PSORS1C1 was hypomethylated." (PMID 36319514, 2023).
systemic sclerosis (5 papers, 2012 to 2024). A chronic disorder, possibly autoimmune, marked by excessive production of collagen which results in hardening and thickening of body tissues. "Studies have shown that TNFSF4 rs2205960 and rs844648 SNPs are associated with the susceptibility to systemic sclerosis." (PMID 30797237, 2019). "Recent studies have demonstrated that polymorphisms of TNFSF4 (rs2205960, rs844644, and rs844648) are associated with SLE and systemic sclerosis (SSc)." (PMID 28470010, 2017).
HCMV infection (4 papers, 2014 to 2022). "In this study, we explored the association between donor SNPs of co-stimulatory genes (CTLA4, CD28, TNFSF4, and PDCD1) and the mortality, CMV infection, GVHD, and relapse of their corresponding recipients in the Taiwanese population." (PMID 34671352, 2021). "With the importance of co-stimulatory signals in the immune system and transplantation tolerance, the associations of the four co-stimulatory genes including CTLA4, TNFSF4, CD28, and PDCD1 with the mortality, relapse, CMV infection, and GVHD after HSCT were analyzed in this study." (PMID 34671352, 2021). "In this study, we investigated further whether these is an association between 34 donor SNPs in the four co-stimulatory genes (TNFSF4, CTLA4, CD28, and PDCD1) and the occurrence of adverse outcomes (mortality, relapse, CMV infection, and GVHD) for patients with AML and ALL." (PMID 34671352, 2021).
uveitis (4 papers, 2013 to 2020). An inflammatory process affecting a part of or the entire uvea. "Only one report has addressed the association of TNFSF4 (a member of the TNFSF) with the two main causes of uveitis, and thus little is known about the associations of other TNFSF and TNFRSF SNPs with the two diseases." (PMID 29285231, 2017). "Further studies should be performed to investigate whether TNFSF4 is also involved in the pathogenesis of other uveitis entities." (PMID 27872495, 2016). "We showed that rs1234315 SNP or rs12039904 of TNFSF may play a role in the susceptibility for BD and VKH but we cannot rule out that other as yet not identified SNPs in the TNFSF4 gene may also be associated with these two uveitis entities." (PMID 27872495, 2016).
Crohn disease (3 papers, 2014 to 2023). A gastrointestinal disorder characterized by chronic inflammation involving all layers of the intestinal wall, noncaseating granulomas affecting the intestinal wall and regional lymph nodes, and transmural fibrosis. "Additionally, TNFSF4 was found specifically expressed in tonsils, lung and colon ILC3 but not in other ILC subsets, supporting previous observation showing that intestinal ILC3 isolated from patients with Crohn’s disease expressed OX40L." (PMID 34885076, 2021).
cystic fibrosis (3 papers, 2013 to 2020). Autosomal recessive disorder caused by pathogenic variants in the CFTR gene (cystic fibrosis transmembrane conductance regulator), which encodes a chloride and bicarbonate channel expressed in epithelial cells, and follow the diagnosis criteria. "Similarly, Kreindler and coworkers reported that vitamin D3 attenuated in a TNFSF4-dependent manner Th2 immune responses to A. fumigatus mounted by CD4+T cells from cystic fibrosis patients with allergic bronchopulmonary aspergillosis." (PMID 33374839, 2020).
HIV-1 infection (3 papers, 2006 to 2017). The type species of lentivirus and the etiologic agent of acquired immunodeficiency syndrome (AIDS). "APOBEC3B is able to suppress the infectivity of HIV-1, while stimulation of TNFSF4 (tumor necrosis factor receptor superfamily, member 4) by its ligand enhances HIV-1 infection." (PMID 17014716, 2006).
Sjögren's syndrome (3 papers, 2008 to 2024). "In humans, the genetic variants of TNFSF4 (TNF superfamily member 4) gene were significantly associated with the primary Sjögren’s syndrome." (PMID 36496760, 2022).
Stroke (3 papers, 2012 to 2020). Sudden impairment of blood flow to a part of the brain due to occlusion or rupture of an artery to the brain. "Therefore, our analyses reflect the association between TNFSF4 polymorphism and stroke." (PMID 30797237, 2019). "Several studies have shown that immune responses including IL6, IgA, CXCL16, TNFSF4, and IL10 were involved in stroke." (PMID 31899762, 2020).
acute myeloid leukemia (2 papers, 2023 to 2024). Acute myeloid leukemia (AML) is a group of neoplasms arising from precursor cells committed to the myeloid cell-line differentiation. "Regarding TNFSF4, it was discovered that rs1234314 and rs45454293 of TNSFS4 were associated with post-HSCT GVHD III-IV in acute myeloid leukemia (AML) patients in our previously published HSCT (including bone marrow transplantation and peripheral blood stem cell transplantation) research analysis." (PMID 36983159, 2023).
bronchiectasis (2 papers, 2020 to 2021). Segmental, irreversible dilation of the bronchial tree resulting in the accumulation of secretions which leads to obstruction. "A recent study identified different inflammation profiles when comparing gingival tissues of bronchiectasis patients having chronic periodontitis, with 7 genes significantly altered in bronchiectasis patients (LTA, LTB, TNFSF4, TNFSF11, TNFSF13, TNFSF13B, and TNFRSF11B)." (PMID 34765263, 2021).